LATS2 (large tumor suppressor kinase 2)
Diseases named in the same sentence as LATS2 in open-access papers (continued):
Sharing a sentence is not in itself a finding about the gene and the disease.
tumor (continued). "Additionally, they found that miR-93 might promote invasion and tumor angiogenesis by silencing LATS2 expression." (PMID 34778378, 2021). "Furthermore, these data suggest that reduced activity of Hippo-kinases such as LATS1 and LATS2 could serve to circumvent RASSF1A-mediated tumor suppressive mechanisms." (PMID 34831091, 2021). "Taken together, LATS2 may play central roles in the regulation of anti-tumor immunity." (PMID 34699318, 2021). "In this study, we discovered that LATS2 is a direct downstream target gene of miR-31-5p, and we demonstrate that miR-31-5p expression is significantly downregulated in parental tumors and cells compared with its expression in OR-LoVo tumor tissues and cell lines." (PMID 31623173, 2019). "However, LATS2 may undermine the ability of retinoblastoma protein to induce a permanent cell cycle arrest in tumor cells." (PMID 30046387, 2018). "Additionally, restoration of siRNA/LATS2 significantly increased tumor volume." (PMID 29145896, 2017). "However, LATS1 null animals develop tumours, and immortalised LATS2 null MEFs display loss of contact inhibition, indicating that LATS1/2 might function as tumour suppressors in mammals." (PMID 23985307, 2013). "It reduces the expression of large tumor suppressor kinase 2 (LATS2), a core kinase within the Hippo signaling pathway, and subsequently promotes CRC cell multiplication and tumor growth by inhibiting the Hippo pathway." (PMID 40565284, 2025). "Its oncogenic role involves promoting tumor proliferation and invasion by suppressing targets such as LATS2, which facilitates cell proliferation, and FIH, which aids in hypoxia-driven tumor progression." (PMID 41002715, 2025). "Additionally, the protein levels of GLUT1, LDHA, HK2 and VEGF in tumor tissues declined with melittin treatment compared with the hypoxia group, and the levels of these proteins were remarkably increased in the hypoxia+melittin+si-LATS2 group compared to that in the hypoxia+melittin group." (PMID 38889502, 2024). "LATS2, a core kinase of the YAP/Hippo pathway, has emerged as a key regulator of several oncogenic or tumor-suppressive regulators, as well as a mediator of EMT in the process of cancer metastasis." (PMID 38273088, 2024). "LATS2 is a core element of the Hippo/YAP axis, a highly conserved signaling pathway, and plays a vital role in tumor growth, invasion and metastasis, epithelial‐mesenchymal transformation, chemotherapy resistance, and tumor immune escape." (PMID 39166861, 2024). "Recent research demonstrated that miR-183-5p can increase HCC cell proliferation by suppressing the expression of tumor suppressors (including AKAP12, DYRK2, FOXN3, FOXO1 and LATS2) which is agreement with our results." (PMID 37168369, 2023). "Immunohistochemistry showed that S1PR1 and p-histone H3 (marker of proliferation) protein levels were significantly decreased, whereas LATS1, LATS2, P62, and cleaved caspase-3 protein levels were significantly increased in S1PR1 knockout tumor tissue." (PMID 37828220, 2023). "ALKBH5 restrained tumor growth and metastasis by downregulating YTHDFs-mediated YAP expression and suppressing miR-107/LATS2–mediated YAP activity in NSCLC." (PMID 37919739, 2023). "MiR-93 regulates tumor angiogenesis by suppressing various targets including VEGF, IL-8, epithelial protein lost in neoplasm (EPLIN), large tumor suppressor, homology 2 (LATS2) and integrin-β8." (PMID 35499045, 2022). "In addition, LATS2 may be involved in cell migration, adhesion (Läubli and Borsig, 2019), and connection, which are closely related to tumor occurrence and development." (PMID 36118851, 2022). "miR-93 is involved in tumor angiogenesis by inhibiting several targets, particularly VEGF, EPLIN, integrin-β8, IL-8, and LATS2 in TNBC tissues." (PMID 34778378, 2021).
tumor (continued). "Previous evidence also demonstrated that LATS1/LATS2 deletion in tumors, which activates YAP signaling, induced increased tumor immunogenicity, leading to tumor destruction by enhancing anti-tumor immune responses." (PMID 33805359, 2021). "Alkylation Repair Homolog 5 (ALKBH5) inhibits tumor growth and metastasis by reducing m6A modification of YAP and suppressing activity of miR-107/Large Tumor Suppressor Kinase 2 (miR-107/LATS2)-mediated YAP." (PMID 33692959, 2021). "The present study revealed that LATS2 mRNA expression and protein expression were decreased in CRC tissues and tumor cell lines by qRT-PCR and TMA immunohistochemistry." (PMID 34699318, 2021). "Previous reports showed that EZH2 targets a cascade of tumour suppressors, such as CDX1, FOXC1, LATS2, CDH1 and DAB2IP." (PMID 33336896, 2021). "The results indicated that LATS2 expression was down-regulated in CRC tissues and clearly related to tumor differentiation (P = 0.002) and TNM stage (P = 0.002)." (PMID 34699318, 2021). "Immunochemical assays and western blotting indicated that TAZ knockdown upregulated the levels of LATS2 and GAS1 in tumor tissue and that miR-942-3p reversed these trends." (PMID 33499877, 2021). "Supporting the notion, PD-L1 (encoded by CD274) is the most significantly upregulated protein in LATS2-mutant MPM, and LATS1/2 deletion has recently been shown to enhance anti-tumor immune responses." (PMID 32824422, 2020). "LATS2, as a member of the LATS family located at 13q11-q1221,22, mainly regulates cell cycle progression to inhibit tumor occurrence and development." (PMID 33268767, 2020). "From these results, we found that transcript expression of SAV1 was downregulated by 1.65-fold (p = 0.003), LATS2 by 1.95-fold (p = 0.010) and YAP1 by 1.4-fold (p = 0.007) in tumor samples compared with CC samples." (PMID 32218280, 2020). "We identified six survival-related genes, EMP1, TPM1, NRP2, FGFR1, CAVIN1, and LATS2, found in the DEG analyses of both, tumor-paracancerous and paracancerous-normal differentially expressed data sets." (PMID 32695477, 2020). "The presented findings suggest m6A demethylase ALKBH5 inhibits tumor growth and metastasis by reducing YTHDFs-mediated YAP expression and inhibiting miR-107/LATS2–mediated YAP activity in NSCLC." (PMID 32106857, 2020). "Collectively, the nude mice experiments showed that circ_0000140 inhibited tumor formation and lung metastasis via EMT possessed by targeting miR-31 to repress LATS2-mediated Hippo signaling pathway." (PMID 32041942, 2020). "The Hippo signaling pathway is a tumor inhibition pathway that was discovered in recent years, of which LATS1 and LATS2 kinase are two important components and have many important biological functions." (PMID 32423384, 2020). "In conclusion, our data provide the evidence that CRNDE play important roles in HCC that is related to mediate epigenetic suppression of multiple tumor suppressive genes, especially CELF2 and LATS2." (PMID 32826865, 2020). "For example, miR-150 and miR-372 can promote the proliferation and growth of Breast Neoplasms cells by targeting the pro-apoptotic purinergic P2X7 receptor and LATS2 respectively." (PMID 33193744, 2020).
tumor (continued). "However, since Hsp90 also chaperones some tumor suppressive proteins such as interferon regulatory factor 1, LATS1 and LATS2 kinases, shepherdin’s inhibition on Hsp90 might deregulate tumor suppressor pathways, which might be one of the reasons why shepherdin failed in clinical application." (PMID 32381104, 2020). "Recent findings in cancer research point to a role of this seed sequence in reinforcing the proliferative cellular program in a wide range of cancers, by repressing tumor suppressor genes such as PTEN, RBL2, LATS2, or CDKN1A." (PMID 30713549, 2018). "Tamoxifen treatment retarded tumor growth in all genotypes; however, Lats1-CKO PyMT tumors were relatively less inhibited than WT-PyMT or Lats2-CKO PyMT tumors." (PMID 30456386, 2018). "The scaffold protein RASSF1A is an important tumor suppressive regulator of the Hippo kinases MST1/MST2 and the large tumor suppressor kinases LATS1/LATS2." (PMID 29179447, 2017). "The primary orthotopic tumour weight was increased by 2.2, 2.1 and 6.2-fold in TP53INP1, LATS2 and CD44 silenced MIA PaCa-2 cells, respectively." (PMID 23857777, 2013). "Concurrently, LATS2 expression in the tumor tissues of the Exo-A375-NC inhibitor group decreased relative to the PBS control group, while the co-administration of miR-424-5p inhibitor increased LATS2 levels." (PMID 39866229, 2025). "Additionally, accumulating studies have confirmed that the m6A demethylase ALKBH5 inhibits tumor growth, metastasis, invasion, and tumor angiogenesis in NSCLC by reducing YTHDFs-mediated YAP1 expression and inhibiting miR-107/LATS2-mediated YAP1 activity." (PMID 38053093, 2023). "The rapid molecular evolution of LATS2 and BIK suggests that these genes may contribute to bat molecular adaptations in tumor suppression." (PMID 37728212, 2023). "In the present study, increased expression of phosphorylated Mst1, LATS2 and YAP1 was observed in CRC cells overexpressing MT2A, and similar results were also observed in subcutaneous CRC tumor and liver metastasis tissues overexpressing MT2A according to immunohistochemical staining." (PMID 35642057, 2022). "In tumor immunotherapy for ESCC patients, patients with high expression of LATS2 may benefit more from this treatment." (PMID 36118851, 2022). "Next, we selected several EZH2 or LSD1 potential targets (P15, P21, KLF2, PTEN, KLF2, LATS2, RND3, and NKD2) with tumor-suppressive role, and hypothesized that some of which might be associated with LINC00665-mediated carcinogenicity." (PMID 34094920, 2021). "This study effectively determined that BAP1, CDKN2A and NF2 alterations occur in pleural effusion-derived tumour cells at a higher frequency than what is typically seen in MM tumour samples, as well as identifying high frequency alterations for the TRAF7 and LATS2 genes." (PMID 34900693, 2021).
tumor (continued). "Downregulated genes such as LATS2, CDC14A and CAPN2 are known tumor-suppressive molecules which could enhance cell cycle progression, cell mobility and reduce apoptosis." (PMID 34654826, 2021). "LATS2 is down-regulated in CRC and related to tumor differentiation and TNM stage." (PMID 34699318, 2021). "The non-sRCCs were predominantly higher risk tumours; only 14 of the 268 (5%) had Hippo pathway alterations, involving NF2 (6/268), FAT1 (3/268), LATS1 (2/268), LATS2 (3/268) and YAP1 (1/268)." (PMID 31959902, 2020). "A LATS2 in-frame deletion insertion missense variant, SL425PP, was detected in the SB tumor from F8 that did not harbor NF2 or chromosome 22 alterations, raising the possibility of independent mutations in the NF2-Hippo pathway in this ED group." (PMID 31963394, 2020). "Our data also argue that LATS2 and NF2 may exert distinct roles in MPM, at odds with the long-held assumption that they act as tumor suppressors through the Hippo pathway." (PMID 32824422, 2020). "Therefore, m6A demethylase ALKBH5 inhibits tumor growth and metastasis by reducing YTHDFs-mediated YAP expression and inhibiting miR-107/LATS2–mediated YAP activity in NSCLC." (PMID 32106857, 2020). "Moreover, several tumor suppressors, including BTG2, TUSC1, BAK1, LATS2, FZD6 and PPP2R1B, were regarded as common targets of TET3." (PMID 32209730, 2020). "Next, we selected several EZH2 or LSD1 potential targets (P15, P21, KLF2, PTEN, TFPI2, LATS2, E-cadherin, and RND3) with tumor-suppressive role, and hypothesized that some of which may be associated with AGAP2-AS1-mediated carcinogenicity." (PMID 31186379, 2019). "As a key serine/threonine kinase in the Hippo signaling pathway, LATS2 phosphorylates the Hippo downstream effector YAP oncoprotein, reduces the level of YAP, and inhibits its shuttling from the cytoplasm to the nucleus, to exert its tumor-suppressive effects." (PMID 31316723, 2019). "Next, we selected several EZH2, LSD1 or DNMT1 potential targets (P15, P21, LATS2, RND1, KLF2, NKD2, PTEN) with tumor-suppressor function and SPRY4, and hypothesized that they may involve in the contributions of SPRY4-IT1 to CCA progression." (PMID 29642935, 2018). "Besides, we measured expression levels of LATS2 and TAZ protein in ESCC cells in vivo using immunohistochemistry analysis resected tumor tissue sections." (PMID 29145896, 2017). "To reveal the physiological role of this negative feedback regulation, we deleted Lats2 or Lats1 in the liver-specific Sav1-knockout mouse model which develops a YAP-induced tumor." (PMID 27006470, 2016). "Furthermore, we identified tumour suppressors, including BTG2, TUSC1, BAK1, LATS2, FZD6 and PPP2R1B, as common targets of TLX and TET3." (PMID 26838672, 2016). "SIAH2 was shown to lead to LATS2 destabilization and YAP activation in hypoxic cells, an effect that provides a tentative connection between ATF4 and HIPPO pathway in stressed cells in the tumor microenvironment." (PMID 27409837, 2016). "Such an analysis of human large tumor suppressor genes, LATS1 and LATS2, has been carried out and the results support a role of hLATS1//2 as negative growth regulators and tumor suppressors." (PMID 25482410, 2015). "Furthermore, tumours from the TP53INP1, LATS2 and CD44 silencing group showed increased cell proliferation as indicated by the strong staining of Ki67, compared with that of the MIA-V group." (PMID 23857777, 2013). "The majority of the tumours from the TP53INP1, LATS2 and CD44 silencing group were poorly differentiated, and the tumour area percentage were more than 80%, while most of the tumours from the MIA-V control group were well differentiated, and the tumour area percentage were less than 20%." (PMID 23857777, 2013).
tumor (continued). "Likewise, other kinases with intrinsic tumor suppressor functions, such as LKB1 and LATS2, can also be suitable targets for agonist development." (PMID 22916121, 2012). "MST1 was related to age (P = 0.002) and tumor size (P = 0.007), YAP expression was related to gender, smoking, and grade (P = 0.033, 0.033, 0.006, respectively), SMAD3 was related to family history and grade (P = 0.004, ˂ 0.001), LATS2 was related to age (P = 0.024)." (PMID 38589525, 2024). "Moreover, in NSCLC, PCAT6 transcriptionally impairs large tumor suppressor kinase 2 (LATS2) promoter activity by binding to EZH2, which mediates H3K27 trimethylation and accelerates the cell cycle, promoting cell proliferation, tumor growth and metastasis, and hindering cell apoptosis." (PMID 34885209, 2021). "Therefore, interactions between LATS2 and YAP1 may be a potential mechanism for regulation of the tumor microenvironment in CRC, although further studies are necessary to confirm this hypothesis." (PMID 34699318, 2021). "Multiple clonal forebrain tumours, originating invariably at the ependymal layer were found in all LATS1/2 cKOs, but not in controls or individual LATS1 cKOs or LATS2 cKO at P20 (18/18 dual knockout, 0/3 LATS1 cKO, 0/3 LATS2 cKO, 0/6 controls), indicating redundancy between LATS1 and LATS2." (PMID 32404936, 2020). "In conclusion, this is the first study demonstrating that circ_0000140 acts as a tumor suppressor that inhibits tumorigenesis and metastasis in OSCC, enforcing its inhibitory function by deactivating miR-31 to up-regulate the key component of the Hippo pathway network, LATS2." (PMID 32041942, 2020). "Furthermore, we chose several EZH2 or LSD1 potential targets (P15, P21, LATS1, LATS2, RND1, KLF2, E-cadherin, PTEN, ASPP2 and RRAD) with tumor-suppressor function, and hypothesized that they may involve in the contributions of AGAP2-AS1 to NSCLC progression." (PMID 27195672, 2016). "The tumor suppressors genes such as EFNA1 (Ephrin-A1), ERRFI1 (ERBB Receptor Feedback Inhibitor 1), LATS2 (Large Tumor Suppressor Kinase 2) and PLK2 (Polo-Like Kinase 2) also show higher average expression in PD0325901 resistant cell lines and thus may be contributing to PD0325901 resistance." (PMID 27030518, 2016). "To recapitulate the tumorigenic phenotype shown in the mouse model in which negative feedback on YAP/TAZ is ablated, we characterized tumor-associated cellular phenotypes in the AML-12 normal mouse liver cell line after depletion of SAV1, LATS1, and/or LATS2 proteins with shRNA constructs." (PMID 27006470, 2016). "In addition to LATS2, many other tumor suppressors such as PPP6C, DKK1, TNFAIP1 and TP53INP1 are also verified as direct targets of miR-373, implying that miR-373 promotes cell proliferation and tumor growth under certain conditions." (PMID 25990556, 2015). "Therefore, it is not difficult to understand that the aberrant expression of LATS2 in cells may lead to tumor occurrence." (PMID 34575133, 2021). "Moreover, the expression of LATS2 and p-YAP1(Ser127) increased, whereas YAP1, Axl, c-Myc, Cyr61, MMP-2 and MMP-9 expression levels were simultaneously decreased in amlexanox-treated group relative to the DMSO-treated group, which was consistent with the subcutaneous tumor tissues results." (PMID 29048430, 2017). "Evaluation of the tumor suppressors, LATS1/2, the direct upstream regulators of Hippo/YAP and TAZ, showed that LATS1 was significantly reduced, whereas LATS2 was not affected." (PMID 35995996, 2022). "LATS1 and LATS2 are serine/threonine kinases that are direct negative regulators of YAP, playing a pivotal role in organ size control and tumor suppression by restricting proliferation and promoting apoptosis." (PMID 33477668, 2021).
tumor (continued). "Interestingly, also a number of oncogenes is up regulated by E2 (MERTK, RET and its ligand ARTN), and several (putative) tumor suppressor genes are down regulated by E2 (BLNK, LATS2, RPRM) that are not, or less, regulated by EGF." (PMID 24758408, 2014).